TNF (tumor necrosis factor)
Diseases named in the same sentence as TNF in open-access papers (continued):
Sharing a sentence is not in itself a finding about the gene and the disease.
Sepsis (continued). "Sepsis relieves the inhibitory mechanisms and releases various other factors like TNF, iNOS, or glucose and confers proinflammatory function to microglia, which produce a range of proinflammatory and neurotoxic factors, thereby expanding inflammatory responses and neuronal damage in the CNS." (PMID 36062193, 2022). "However, HRS given as early as 1 h after LPS-induced sepsis was more effective in decreasing TNF-α and IL-1β expression levels and increasing IL-10 levels compared to other time intervals (p < 0.05)." (PMID 36435787, 2022). "HgSMs are characterized by the simultaneous increased release of inflammatory and anti-inflammatory mediators, such as TNF-α and IL-10, indicative of a condition that has been termed as immunoparalysis, as it occurs in patients affected by sepsis and septic shock." (PMID 35247131, 2022). "The effect of anti-TNF-α in sepsis has been documented in animal models." (PMID 33435569, 2021). "A recent study reported that inhibition of TNF-α and IFN-γ could improve death rate caused by COVID-19 infection, sepsis, and cytokine shock." (PMID 34725309, 2021). "In addition, serum cytokine levels of IL-1β, IL-6, IL-8, IL-10, IL-12, IL-17A, IL-18, IFN-γ, TNF-α, and calprotectin were found to be elevated in sepsis." (PMID 34654467, 2021). "In this study, we analyzed the diagnostic value of sIL-2R, TNF-α, and PCT in sepsis patients." (PMID 34745113, 2021). "Additionally, during sepsis, DCs produce lower levels of pro-inflammatory cytokines (such as IL-12 and TNF-α) and higher levels of anti-inflammatory cytokines (such as IL-10 and TGF-β)." (PMID 34335278, 2021). "In the presence of sepsis in the intestine, endotoxin stimulates intestinal mucosal mast cells to release TNF-α, which in turn triggers an inflammatory cascade by activating macrophages and produces a large number of proinflammatory cytokines to promote inflammation." (PMID 34790828, 2021). "To highlight our finding also under pathological situations, we induced PC migration by the inflammatory cytokine tumor necrosis factor alpha (TNFα), which is known to be upregulated in several diseases and associated with BBB breakdown in conditions such as ischemic stroke, meningitis and sepsis." (PMID 34571963, 2021). "Sepsis elevated IL-10 and TNF-α among WT mice, but this effect was lost among PD1−/− murine lungs." (PMID 33746973, 2021). "However, in sepsis patients, GM-CSF restored the HLA expression on mononuclear cells, and increased TNF release by white blood cells after LPS stimulation." (PMID 34335278, 2021). "In addition, researchers also found that electrical vagus nerve stimulation during sepsis reduced the level of TNF-α by activating an anti-inflammatory mechanism." (PMID 34499695, 2021). "Determination of GM-CSF and TNF-α levels in combination may represent a biomarker for the differential diagnosis of FMF from sepsis, based on measurement of multiple cytokines." (PMID 34654467, 2021). "Interestingly, FFP transfusion has been found to decrease both TNF-α and sydencan-1 levels in critically ill human patients, 45% of which had sepsis." (PMID 33718468, 2021). "Similarly, other SNPs such as TNF−α (–308, −238, +489) showed a significant difference between sepsis and acute septic shock patients." (PMID 34692772, 2021). "Consequently, we measured the production of IL-6, TNF-α and IL-1β in sepsis patients and healthy controls and in PBMCs under in vitro LPS stimulation to investigate the effect of the NLRP3 29940 G>C variation on the production of these related cytokines." (PMID 34172780, 2021). "Furthermore, endogenous LIF attenuates acute inflammatory responses and downregulates TNFα synthesis in LPS-induced sepsis mice." (PMID 34074039, 2021). "Thus, in the FMF group, FGF-2, GM-CSF, MIP-1β, and TNF-α form interrelated networks, whereas in the sepsis group, IFN-γ, TNF-α, IL-8, and MIP-1α form interrelated networks." (PMID 34654467, 2021).
Sepsis (continued). "Similarly, the infusion of dexmedetomidine in sepsis patients following abdominal surgery attenuated the degree of increase in the levels of TNF-α, IL-1, and IL-632." (PMID 34040043, 2021). "In addition, STS has been shown to suppress the release of IL-6 and TNF-α in a mouse model of sepsis." (PMID 34122723, 2021). "Elsewhere, in a mouse model, it has been found that the cytokines produced during sepsis, such as tumor necrosis factor-α (TNF-α), interleukin-β (IL-β), and interferon-γ (IFN-γ), significantly decrease the expression of SGLT2, SGLT3, and GLUT2 and significantly increase that of SGLT1 and GLUT1." (PMID 34948317, 2021). "Only sIL-2R and TNF-α in patients with sepsis related to other laboratory indicators were higher than PCT, which may be related to differences in the sensitivity and specificity between projects." (PMID 34745113, 2021). "Haplotype variations related to TNF-α can prevent patients with SIRS from developing sepsis." (PMID 34335278, 2021). "In the early stage of sepsis, macrophages promote host defense by eliminating invading pathogens or damaged tissues and releasing abundant amounts of proinflammatory cytokines, such as TNF-α, IL-1β, and IL-6." (PMID 34220338, 2021). "However, C5a, as shown in a sepsis in vitro study, also decreased NFκB-dependent gene transcription of TNFα and impaired lipopolysaccharide-induced TNFα production in neutrophils." (PMID 33803624, 2021). "Placental cytokine levels (TNF-α, IL-1β, IL-6) were also increased at 24 h after sepsis induction." (PMID 33632243, 2021). "In an in vivo sepsis study, RvD1 decreased IL-6, TNFα, IL-1β and IFNγ levels significantly." (PMID 33815391, 2021). "Sepsis resulted in elevation of TNF-α, IL-10, KC, and MCP-1 concentrations in obese mice." (PMID 33859538, 2021). "Not only TNF, but also other host mediators are involved in sepsis pathogenesis." (PMID 33546401, 2021). "Inflammatory factors such as tumor necrosis factor-alpha (TNF-α), interleukin-6 (IL-6), and interleukin-1 (IL-1) act as key regulators of the immune response and play a critical role in the complex pathophysiological mechanisms of sepsis." (PMID 34867346, 2021). "Besides, the injection of miR-378a-3p antagomir hindered the inflammatory response augment induced by sepsis, presenting as the downregulation in TNF-α, IL-1β, IL-6 (P < 0.05)." (PMID 34565302, 2021). "IL-8 and TNF-α, produced by monocytes-macrophages, can promote the body’s inflammatory response and reflect the degree of inflammation, which are considered as vital indicators for the diagnosis of sepsis." (PMID 34388113, 2021). "Comparatively, TNF-α could be reduced by baicalin (MOL002776) in the blood of sepsis mice and was reduced by beta-sitosterol [MOL000358 (CS, DG, and HH)], caffeic acid [MOL000223 (CX, DS, and HH)]." (PMID 34938184, 2021). "In addition, sepsis increases the concentration of inflammatory factors (such as IL-6, TNF-α, HMGB1), which are the main inducers of apoptosis." (PMID 34057015, 2021). "Besides, the blood D-lac and TNFα concentration also increased in a time-dependent manner after sepsis." (PMID 34039427, 2021). "Interferon gamma (IFN-ɣ) increases tumor necrosis factor production in patients with sepsis." (PMID 33803628, 2021). "Regarding the intermediate monocytes, such an exaggerated elevation has been shown in severely injured patients 48 h post-trauma and under inflammatory conditions such as sepsis or bacterial and viral infections, paralleled by sequestration of high amounts of TNF-α, IL-1β, and IL-6." (PMID 34575249, 2021). "Results confirmed that inhibition of miR-378a-3p expression could significantly reduce the level of TNF-α, IL-1β, IL-6 in the serum of sepsis rats, and thus improved the inflammatory response induced by sepsis." (PMID 34565302, 2021). "There is also a reduction in LPS-induced TNF-α secretion from monocytes in sepsis, and these patients may benefit more from an immune adjuvant therapy such as G-CSF." (PMID 34485339, 2021).
Sepsis (continued). "In sepsis patients, JKAP level negatively associated with TNF-α, IL-1β, and IL-17 expressions." (PMID 33083958, 2021). "In summary, we have demonstrated the PEGylated catalase can effectively regulate the production of cytokines by leukocytes, suppress the elevated level of AST, ALT, TNF-α, and IL-6 and mitigate the damage to the liver, kidney, lung function and other organs in mice with induced sepsis." (PMID 34888304, 2021). "Existing research has identified the ability of miRNAs to participate in the regulation of sepsis by targeting the tumor necrosis factor, a primitive regulator of the pro-inflammatory process in sepsis, and the toll-like receptors which mediate systemic inflammation to pathogens in sepsis." (PMID 34654440, 2021). "Some researchers believe that the main role in damage to cardiomyocytes in sepsis is played by inflammatory mediators, such as tumor necrosis factor-alpha (TNF-ɑ), interleukins (IL-1, IL-6), and bacterial exo- and endo-toxins, which have a direct cytotoxic effect on cardiomyocytes." (PMID 34575063, 2021). "Moreover, it has been documented that the plasma levels of TNF-α and IL-6 increased significantly in patients with sepsis and in animal models." (PMID 35003518, 2021). "This suggested that DEX could reduce the levels of TNF-α, IL-1β, and IL-10 after sepsis induction at the early stage." (PMID 33981237, 2021). "Importantly, the administration of an anti-TNF antibody inhibited the sepsis-induced increase in muscle proteolysis in rats, indicating that TNF is an important regulator of muscle protein breakdown during sepsis." (PMID 34572540, 2021). "Since there was a significantly higher plasma TNF-α level in recruited sepsis patients in comparison to controls (28.6 ± 3.7 vs. 12.4 ± 1.1 pg/mL, P < 0.0001) (data not shown), the septic cellular conditions were mimicked using TNF-α on HCAECs." (PMID 34135769, 2021). "Furthermore, PBMCs with the sepsis-associated risk allele 29940G in NLRP3 exhibited significantly enhanced expression of NLRP3 and release of IL-1β and TNF-α compared to those with the C allele under LPS stimulation." (PMID 34172780, 2021). "Unlike other states where cytokine levels are increased, as in sepsis, the levels of IL-6 and TNF-α in patients with COVID-19 were sustained during days or even weeks, which makes the decision for administering the anticytokine treatment on time more difficult." (PMID 33968298, 2021). "Furthermore, we observed that among the tested sepsis-associated cytokines (e.g., IFN-γ, IL-1β, TNF-α, and G-CSF), G-CSF and IFN-γ impaired DC development from cultured HSPCs." (PMID 34566996, 2021). "The inflammatory factors including TNF-α, IL-6 were increased significantly after sepsis, Mdivi-1 distinctly reduced the levels of TNF-α, IL-6 in serum, myocardial tissue, and vascular smooth muscle tissue, and the phosphorylation of NF-κ B p65 in myocardial tissue and vascular smooth muscle tissue." (PMID 34566637, 2021). "Moreover, plasma MCP-1 levels directly correlate with other cytokine levels (TNF-α, IL-6, IL-8, and IL-10) in the setting of sepsis." (PMID 33803628, 2021). "Therefore, endogenous LIF attenuates sepsis and septic shock and downregulates tumor necrosis factor-α synthesis and release in LPS-induced sepsis mice." (PMID 34074039, 2021). "DG has been reported to effectively inhibit bacterial endotoxin–induced HMGB1 release in vitro and help mice defend against lethal endotoxemia and CLP-induced sepsis, and inhibit pro-inflammatory mediators IL-1β and TNF-α, thereby protecting LPS-induced endotoxic shock in rabbits." (PMID 34938184, 2021). "Interestingly, though, there was a strong positive correlation between sepsis scores and plasma concentrations of IL-6, IFNγ and TNFα." (PMID 34440538, 2021).
Sepsis (continued). "who observed the overexpression of TUG1 could decrease TNF-α expression level and reduce sepsis-induced apoptosis of cardiomyocytes via ing miR-27a, which had a protective effect against sepsis-induced myocardial injury." (PMID 34630395, 2021). "SIRS, characterized by the release of huge amounts of pro-inflammatory cytokines, including tumor necrosis factor-α, interleukin-1β, interleukin-6, and interferon-γ named as “cytokine storm”, has been reported to be correlated with higher mortality in severe sepsis." (PMID 33967773, 2021). "In addition to treating uveitis, ruxolitinib was reported to protect mice from LPS-induced sepsis by suppressing nitric oxide production and the expression of iNOS, TNF-α and IL-6." (PMID 34361917, 2021). "Recently, a comparison of mHLA-DR expression and ex vivo LPS-induced TNF-alpha production and their effect on 28-day outcome and development of secondary infections predictors in severe sepsis was performed in a prospective observational study of 83 adult septic patients." (PMID 34945111, 2021). "In addition, the beneficial effects of monoclonal antibody-based anti-TNF-α, anti-IL-1β, or anti-IL-6 therapy individually on sepsis have previously been reported." (PMID 34065201, 2021). "However, it is important to acknowledge that in the present work we found higher IL-6, IL-8, IL-1 β and TNF- α levels, compared and consistent to those commonly described for sepsis." (PMID 34460840, 2021). "Some laboratory parameters, including serum ferritin, TG, sCD25, IFN-γ, IL-6, IL-10 and TNF-α, could reflect the level of “inflammatory storm, which lead to the “sepsis-like symptoms” and organs injuries in HLH." (PMID 35127776, 2021). "Next, we found that Pellino1 protein could induced the protein expression of Pellino1, TRAF6 and NF-κB and increased the levels of TNF-α, IL-6, IL-1β and IL-18 in mice of sepsis." (PMID 33632252, 2021). "Cytokine levels increased in both groups after sepsis onset (wt: IL-6, p = 0.004; TNF-α, p = 0.008; IL-10, p = 0.008; fD−/−: IL-6, p = 0.001; TNF- α, p = 0.002; IL-10, p = 0.001), whereas IL-6 levels were higher in fD−/− mice compared to wild-type at 3-h (p = 0.012) after CLP." (PMID 34396466, 2021). "Intermittent elevation of TNF-α and IL-1β in inflammatory response and sepsis has been reported." (PMID 34870560, 2021). "The study concluded that ex vivo LPS-induced TNF-alpha production may be superior as an early predictor of clinical outcome in multiple trauma patients with sepsis when compared to mHLA-DR expression." (PMID 34945111, 2021). "Furthermore, it is well established that monocytes contribute to the pathogenesis of sepsis by secreting inflammatory cytokines such as TNF-α, which peaks in the first two hours and falls to undetectable levels after 6 hours." (PMID 34737742, 2021). "In addition, it was observed that administration of tannic acid as an anti-inflammatory agent reduced the levels of inflammatory cytokines, TNF-α and IL-6, in sepsis as it was observed in bone marrow-derived macrophages cells." (PMID 35317115, 2021). "TNFα, IL-6, IFNγ, IL-1β and IL-10 were measured in brain of mice 6 h after induction of sepsis." (PMID 33608025, 2021). "A lot of therapeutic agents have been developed to treat sepsis, including antibodies against LPS, antitumor necrosis factor (TNF) agents, Toll-like receptor 4 (TLR4) antagonists, drugs targeting the coagulation cascade, and drugs targeting platelet-activating factor (PAF)." (PMID 33946374, 2021). "Tumor necrosis factor-α (TNF-α), interleukin-1β (IL-1β), and IL-6 are three major inflammatory cytokines that actively participate in mediating the development of organ injury (e.g., that of the liver) induced by endotoxemia and sepsis." (PMID 34065201, 2021).
Sepsis (continued). "TNF-α is the key inflammatory factor involved in the progression of sepsis." (PMID 33967760, 2021). "As TNFα is a major inducer of GC resistance in sepsis, the recent demonstration that the TNFα/GR antagonism is mediated by reshaping the nuclear GR ́s interactome constitutes a major finding that should allow for development of more specific targeting approaches." (PMID 34576214, 2021). "TNF-α plays a central role in systemic inflammatory response due to its ability to release other cytokines in the early stage of infection and its direct influence on septic shock, and the plasma levels of TNF-α are associated with sepsis-induced death." (PMID 34745113, 2021). "Additionally, blocking the M3 receptor prevented the increase in TNF-α and MCP-1 associated with inflammatory cell infiltration and tissue damage in a sepsis model." (PMID 34299169, 2021). "IL-6, IL-12, IL-1β and TNF-α are important inflammatory cytokines in sepsis." (PMID 33995024, 2021). "Because TGF-β1 inhibits the release of proinflammatory cytokines, such as IL-1 and TNF from monocytes and macrophages, it may be important for immunosuppression often seen in sepsis." (PMID 34572540, 2021). "Indeed, LF was demonstrated to reduce interleukin 6 (IL6) and tumor necrosis factor-alpha (TNFα) in experimental settings simulating sepsis." (PMID 33498631, 2021). "Elevated ratio of IL-10/TNF-α has been observed in adult sepsis data and suggested to indicate sepsis-induced immunosuppression,; it may therefore indicate relative immunosuppression in preterm infants with sepsis." (PMID 32407417, 2020). "Expressed early in the pathogenesis of sepsis, TNF-α is a potential therapeutic target in sepsis." (PMID 33986658, 2020). "TNF-α is a major cytokine involved in the sepsis-related kidney injury." (PMID 33584688, 2020). "One of the main cytokines secreted in response to sepsis is Tumor Necrosis Factor (TNF)-α." (PMID 32226779, 2020). "In the non-clinical study, RJX exhibited potent and dose-dependent protective activity, decreased the inflammatory cytokine responses (interleukin-6, tumor necrosis factor alpha, transforming growth factor beta), and improved survival in the LPS-GalN mouse model of sepsis and ARDS." (PMID 33244300, 2020). "Sepsis-induced AKI is closely modulated by inflammatory cytokines such as tumor necrosis factor α (TNF-α), which could induce most of septic symptoms and signs including AKI." (PMID 32573678, 2020). "Because TNF-α and IL-1β activate endothelial cells during sepsis, we investigated whether other cytokines could similarly induce proinflammatory cytokine and PAI-1 production in endothelial cells." (PMID 32826331, 2020). "MEG3 restrained the activation of TNF-α and IL-6, in sepsis models." (PMID 32410866, 2020). "Tumor necrosis factor-α is a prominent inflammatory cytokine during human SIRS/sepsis." (PMID 32766286, 2020). "One study reported a significantly lower TNFα production capacity in patients who died following sepsis while another reported a significantly higher change in TNFα production capacity on the first day of sepsis from baseline in septic patients who died compared to patients who survived." (PMID 31781831, 2020). "In the CLP-induced sepsis, calcium-sensing receptor activation promotes T cell apoptosis and the secretion of the proinflammatory cytokine TNF-α and the anti-inflammatory cytokine IL-4 probably through NF-κB and partial ERK and JNK signal transduction pathways." (PMID 32908632, 2020). "Our bioinformatics analysis showed that THRIL may interact with miR-19a, which targets TNF-α, a critical player in sepsis." (PMID 32944003, 2020). "Sepsis induces host production of cytokines (interleukin-1β, tumor necrosis factor-α, nitric oxide and reactive oxygen species), which result in dysregulated systemic inflammatory response associated with multiple organ damage and shock e.g., cardiac dysfunction and hepatocellular injury." (PMID 32375857, 2020).